IRX3 (iroquois homeobox 3)
Description:
Transcription factor involved in SHH-dependent neural patterning. Together with NKX2-2 and NKX6-1 acts to restrict the generation of motor neurons to the appropriate region of the neural tube. Belongs to the class I proteins of neuronal progenitor factors, which are repressed by SHH signals. Involved in the transcriptional repression of MNX1 in non-motor neuron cells. Acts as a regulator of energy metabolism.
Synonyms: IRXB1; IRX-1
Tractability: No criterion of Open Targets' tractability assessment is met for any kind of drug.
Gene: Protein-coding gene on chromosome 16 (54,283,304 to 54,286,787, reverse strand). Ensembl gene ENSG00000177508.
Subcellular location: Nucleus
Subcellular location (Human Protein Atlas): Nucleoplasm; Cytosol
Gene Ontology:
Molecular function: sequence-specific double-stranded DNA binding; DNA-binding transcription activator activity, RNA polymerase II-specific; DNA-binding transcription factor activity, RNA polymerase II-specific; DNA-binding transcription repressor activity, RNA polymerase II-specific; RNA polymerase II cis-regulatory region sequence-specific DNA binding; DNA binding
Biological process: atrioventricular bundle cell differentiation; cell development; energy homeostasis; His-Purkinje system cell differentiation; negative regulation of transcription by RNA polymerase II; neuron differentiation; positive regulation of gap junction assembly; positive regulation of transcription by RNA polymerase II; Purkinje myocyte development; regulation of cell communication by electrical coupling involved in cardiac conduction; regulation of transcription by RNA polymerase II; metanephros development; proximal/distal pattern formation involved in nephron development; regulation of DNA-templated transcription; specification of loop of Henle identity
Cellular component: chromatin; nucleus; axon; cytoplasm
Genetic constraint (gnomAD): Loss-of-function variants: 18 observed, 26.61 expected, observed/expected ratio (o/e) 0.68, 90% interval 0.47 to 1. The synonymous counts are far from expectation, so gnomAD's model fits this gene poorly and the ratio says little. Missense variants: 700 observed, 582.83 expected, observed/expected ratio (o/e) 1.2, 90% interval 1.13 to 1.28. Synonymous variants: 391 observed, 281.15 expected, observed/expected ratio (o/e) 1.39, 90% interval 1.28 to 1.51.
Homologues: Orthologues: chimpanzee IRX3 (99% identical), macaque IRX3 (98% identical), dog IRX3 (95% identical), pig IRX3 (94% identical), mouse Irx3 (92% identical), guinea pig IRX3 (86% identical), rat Irx3 (85% identical), tropical clawed frog irx3 (54% identical), zebrafish irx3a (53% identical), zebrafish irx3b (38% identical). Paralogues in human: IRX1 (42% identical), IRX4 (32% identical), IRX5 (31% identical), IRX2 (30% identical), IRX6 (28% identical), MKX (17% identical).
Diseases named in the same sentence as IRX3 in open-access papers:
IRX3 is named in the same sentence as 62 diseases in open-access papers, as found by Europe PMC text mining. Sharing a sentence is not in itself a finding about the gene and the disease. The quoted sentences say what the papers report.
Obesity (153 papers, 2010 to 2025). Accumulation of substantial excess body fat. "IRX3 is linked to predisposition to obesity through the FTO locus and is upregulated during early adipogenesis in risk-allele carriers, shifting adipocyte fate toward fat storage." (PMID 40769964, 2025). "Iroquois Homeobox 3 (IRX3), a highly conserved member of the Iroquois homeobox gene family, has been implicated in obesity through its regulation of fat mass and obesity-associated (FTO) gene." (PMID 41436436, 2025). "In this study, we aimed to gain insight into the molecular mechanisms underlying the obesity-associated enhancer in the FTO locus by uncovering genes that are under direct transcriptional control of IRX3 in developing preadipocytes." (PMID 40769964, 2025). "Genetic variants in an IRX3 enhancer (FTO locus) are reproducibly associated with obesity and type 2 diabetes, though depot-specific roles for IRX3 have not been explored." (PMID 39401200, 2024). "Recent studies suggest that Irx3 and Irx5, in association with intronic variants of fat mass and obesity-associated gene, are determinants of obesity." (PMID 37335434, 2024). "A locus within an intron in the FTO gene, whose variants are reproducibly associated with obesity and type 2 diabetes, is actually an enhancer for the mesodermal developmental transcription factor IRX3." (PMID 39401200, 2024). "Genetic variants in an enhancer for IRX3, a developmental marker of somatic lateral plate mesoderm, are recurrently linked with body fat distribution and obesity." (PMID 39401200, 2024). "Several of the high-confidence genes, including FTO and IRX3, are associated with obesity-related traits." (PMID 37433298, 2023). "These are distinct from the polymorphic intronic sequences of FTO associated with human obesity which have been found to regulate IRX3 expression in adipocytes and hypothalamic neurons." (PMID 37539037, 2023). "A notable example of a distally acting enhancer variant > 50 kb, is the obesity FTO locus variant rs1421085 regulating IRX3 and IRX5, which are 500 kb and 1,163 kb away respectively." (PMID 35365203, 2022). "Similar pleiotropy was observed for FTO obesity variants on the dynamics and lineage-specific expression of distal genes such as IRX3 and IRX5." (PMID 35659055, 2022). "Large-scale clinical research studies demonstrated that a variant of FTO enhances the expression of IRX5 and IRX3 leading to excessive adipocyte differentiation and obesity." (PMID 35428362, 2022). "Genotypes rs8053360 CC and rs1126960 GG were related to body weight and BMI, particularly among female individuals, and the polymorphism rs3751723 in IRX3 has been associated with obesity." (PMID 35957832, 2022). "Genetic analysis results indicated that IRX3 polymorphisms of rs1126960 and rs3751723 were related to obesity." (PMID 35957832, 2022). "Claussnitzer demonstrated that the presence of the homozygous C/C obesity-risk alleles in this FTO locus results in the expression of nearby genes IRX3 and IRX5, thus generating less thermogenic adipocyte phenotype." (PMID 34895148, 2021). "Collectively, these studies suggest that obesity-associated variants of FTO regulate the expression of IRX3 and IRX5 in the hypothalamus and adipose tissue contributing to metabolic changes." (PMID 34795556, 2021). "The exciting role of IRX3 with obesity came into light with the genome-wide association studies, which identified the direct interaction of IRX3 gene promoter with obesity-associated FTO (fat mass and obesity-associated) gene regions." (PMID 34968255, 2021). "The FTO obesity variant circuitry, mediated through IRX3 and IRX5, has been linked to adipocyte browning in humans and thus to mitochondrial function." (PMID 34290091, 2021). "This is the case for the obesity-susceptibility alleles in the first intron of the FTO gene, whose connection to obesity has been linked to their role as a cis-regulatory element of the IRX3 transcription factor." (PMID 33909378, 2021).
Obesity (continued). "The iroquois homeobox 3 (IRX3) gene has been implicated in human obesity and controls body mass and composition in mouse." (PMID 32192102, 2020). "The rs1421085 FTO is related to poor eating behaviors, and rs3751723 IRX3 is associated with obesity." (PMID 32651404, 2020). "Genetic variants of the FTO and IRX3 genes are in high linkage disequilibrium and associated with obesity." (PMID 32651404, 2020). "In our study, IRX3 was significantly higher expressed in samples with FTO obesity-risk alleles and support its suppressive role in thermogenesis." (PMID 32316277, 2020). "The obesity-associated SNPs in the first intron of FTO are functionally connected with the IRX3 gene." (PMID 32651404, 2020). "Instead, the authors detected robust interactions between the obesity-associated interval and the IRX3 gene (located half a megabase downstream)." (PMID 32603637, 2020). "It has also been suggested that the homeobox gene Iroquois homeobox 3 (IRX3) is a functional long-range target of obesity-associated variants within FTO." (PMID 31075924, 2019). "In human obesity, IRX3 is a target of the FTO risk loci with allele carriers having increased IRX3 expression in early adipogenesis where it is proposed to regulate adipocyte function and browning through the modulation of mitochondrial genes." (PMID 31086124, 2019). "Genome-wide association studies of obesity in humans have isolated the FTO/IRX3 locus, where it appears that a variant in an intron of the FTO gene affects body mass index by a regulatory effect on the neighbouring gene IRX3." (PMID 29361907, 2018). "The obesity-associated, single nucleotide alteration enhances IRX3 expression in beige adipocytes, leading to a shift from the energy-dissipating beige adipocytes to energy-storing white adipocytes." (PMID 29914202, 2018). "The Iroquois homeodomain transcription factor gene IRX3 is expressed in the developing nervous system, limb buds, and heart, and transcript levels specify obesity risk in humans." (PMID 29346763, 2018). "rs7195994 is in LD with rs2540767 (r2 = 0.9), which shows chromatin interaction with the IRX3 gene, which some studies have suggested is one of the causal genes for obesity/BMI at the FTO locus." (PMID 30166627, 2018). "For example, polymorphism in the FTO gene are the strongest GWAS signals for obesity, but the functional mechanism of the association appears chiefly due to the effects of the SNPs on two neighbouring genes, IRX3 and RPGRIP1L37." (PMID 29955040, 2018). "We further identified the association between rare nonsynonymous IRX3 variants with human obesity risk." (PMID 28988979, 2017). "Recently, two studies made a breakthrough in identifying IRX3 as the target of the risk loci in the FTO gene for human obesity." (PMID 28988979, 2017). "An alternate explanation for the discrepancy in FTO SNP polymorphisms and regulation of energy expenditure is via the effect of the obesity-associated FTO region on expression regulation of homeobox gene IRX3 (Iroquois homeobox protein 3) and IRX5." (PMID 28859657, 2017). "We aimed to test IRX3's roles in the browning program and to evaluate the association between the genetic variants in IRX3 and human obesity." (PMID 28988979, 2017). "With regard to the close association of IRX3 with the FTO obesity-linked loci, revealing IRX3's genetic profile can be of great importance to explain how genetic factors manipulate body weight alteration." (PMID 28988979, 2017). "In this study, we first revealed the genetic structure of rare variants of IRX3 in relation to obesity." (PMID 28988979, 2017). "To further explore the association of IRX3 with human obesity, we examined IRX3 expression in human adipose tissues and detected significantly reduced IRX3 mRNA levels in the sWAT of obese subjects compared to those of non-obese individuals." (PMID 28988979, 2017).
Obesity (continued). "A recent study has demonstrated that obesity-associated non-coding variants in FTO affect the expression of the gene IRX3 in humans, mice and zebrafish." (PMID 26907388, 2016). "The spatial clustering of FTO and IRX3 is implicated in obesity, by altering the expression of IRX3 expression and consequently mis-regulating body mass." (PMID 27507988, 2016). "For instance, SNP in FTO intron causes obesity by long-range functional connection with IRX3, which testifies the causal role of disease-associated SNPs in non-coding region." (PMID 26868054, 2016). "As an illustration, the obesity-associated FTO sequence directly interacts with the promoters of IRX3 as well as FTO in the human, mouse and zebrafish genomes." (PMID 25825681, 2015). "Recent studies have shown that the SNPs in FTO that are associated with obesity regulate IRX3 expression, which is highly expressed in the brain." (PMID 25177340, 2014). "Importantly, non-coding variation within introns 1 and 2 of FTO (for fat mass and obesity-associated) which sits 200–500KB downstream of IRX3, provides the strongest genetic association for risk of human obesity." (PMID 37539037, 2023). "IRX3 is a known functional long-range target of FTO variants associated with obesity." (PMID 37433298, 2023). "A specific variant inside the obesity-associated region (rs1421085 T→C) abrogates the binding of the ARID5B repressor leading to activation of a strong enhancer that promotes the expression of IRX3 and IRX5 during adipocyte development." (PMID 37539037, 2023). "IRX3 affects obesity, which is associated with higher Cu in serum and tissues." (PMID 36818345, 2023). "IRX3, one of these 13 transcription factors, has been demonstrated to play an important role in the occurrence and development of obesity by participating in the fat mass and obesity associated (FTO) obesity variant mechanism." (PMID 35957832, 2022). "The association of IRX3 variants with obesity has been demonstrated." (PMID 35957832, 2022). "Furthermore, ∼20k-bp deletion spanning the orthologous obesity-associated interval of Fto in mice leads to down-regulation of both Irx3 and Irx5 in preadipocytes and developing hypothalamus." (PMID 34795556, 2021). "While a top variant identified by GWAS was assumed to regulate FTO by a series of functional tests in 2009–2010, in 2014 it was found to interact with the promoters of IRX3 located several hundred kilobases away and obesity-associated variants were associated with IRX3 expression." (PMID 32948841, 2021). "However, it has been reported that FTO genotype had a strong association with obesity via altering the IRX3 gene expression level." (PMID 34399781, 2021). "Although there are differences in the metabolic phenotypes depending on the models, Irx3- and Irx5-deficient mice are generally lean and display an anti-obesity phenotype with elevated energy expenditure due to adipose beiging (i.e., enhanced adipose thermogenesis) compared to wild-type controls." (PMID 34795556, 2021). "Rare mutations in IRX3 were correlated with obesity in humans." (PMID 32649035, 2020). "The iroquois homeobox 3 (IRX3) gene has been implicated in human obesity." (PMID 32192102, 2020). "Interestingly, non-coding variation in an enhancer region 500 kb downstream of IRX3 provides the strongest genetic association with risk for human obesity." (PMID 29346763, 2018). "While FTO is the first risk gene for obesity identified via genome-wide association studies, its exact mechanism remains unknown until two recent studies reported that IRX3, as FTO's target, probably inhibited the browning of white fat." (PMID 28988979, 2017). "Very recently, it was shown that genetic variants within FTO gene are linked functionally to another distant gene called IRX3 which may link the association of FTO SNPs with both obesity and T2DM." (PMID 28915859, 2017).
Obesity (continued). "Therefore, we further conducted targeted sequencing of IRX3 coding sequence in the lean and young obese subjects and found that rare IRX3 variants were significantly associated with human obesity." (PMID 28988979, 2017). "In total, 19 obese patients and 9 lean subjects (2.21% vs. 0.98%) had rare nonsynonymous IRX3 variants (P = 0.038; OR = 2.27; 95% CI, 1.02–5.05), indicating that rare nonsynonymous variants of IRX3 were associated with the development of human obesity." (PMID 28988979, 2017). "Moreover, a classical example is obesity-associated SNP (rs9930506), which gives rise to obesity by regulating the expression of IRX3 through long-range connection." (PMID 26868054, 2016). "If FTO variants confer obesity risk by driving the expression of IRX3, one may expect increased expression of IRX genes in obese subjects." (PMID 27560134, 2016). "The intronic SNPs associated with human obesity may influence adiposity through effects on the expression of other neighbouring genes including IRX3 and RPGRIP1L." (PMID 25830092, 2015). "A third explanation for heterozygote advantage could be even the involvement of an additional factor or an interaction of the IRX3 promoter with the obesity-associated SNP region of FTO." (PMID 26431034, 2015). "Whereas direct effect of rs9939609 on FTO function is possible, recently it has been suggested that at least for obesity the associated FTO region exerts its effect modulating expression of another relatively distant gene - IRX3 which encodes a transcription factor highly expressed in brain." (PMID 25265168, 2014). "Smemo and colleagues report that the region encompassing the SNPs form long-range connections with the promoter of the downstream IRX3, and that the obesity-associated SNPs in FTO intron 1 are associated with expression of IRX3, but not FTO, in samples of human cerebellum." (PMID 25242086, 2014). "However, it later transpired that the focus on the closest gene was inappropriate and that obesity association for this locus is, at least in large part, due to altered regulation of a neighbouring gene, iroquois homeobox 3 (IRX3), which has an impact on peripheral adipocyte metabolism." (PMID 33233816, 2020). "Additionally, using chromatin conformation capture technologies, the region has been observed to establish long-range interactions with the obesity-related gene IRX3 and FTO risk alleles correlating with increased IRX3 expression and body mass index in humans, mice, and zebrafish." (PMID 32486876, 2020). "Moreover, because this study shows that complete knockout of IRX3 is lethal to pigs, whether targeted regulation of IRX3 for the purpose of treating human obesity also causes severe adverse consequences requires further investigation." (PMID 32192102, 2020). "While neither our study nor the prior UK Biobank GWAS of lung function could assign a candidate gene to the FTO region variants based on colocalization with eQTL or other approaches, studies have linked obesity-related FTO variants to expression of the distal genes IRX3 and IRX532." (PMID 33057025, 2020). "One of the most accepted hypotheses to explain the molecular mechanism takes into consideration that the expression regulation of FTO and other nearby genes (RPGRIP1L and IRX3) is a process controlled by an obesity‐associated region in intron 1 of FTO, which we also replicated in this study." (PMID 31033179, 2019). "However, whether the genetic variants of IRX3 are associated with human obesity and how IRX3 regulates the browning process remain unclear." (PMID 28988979, 2017). "As such, IRX3 might interact with other obesity-related genes or environmental factors in a complicated manner to determine the penetrance for obesity, although its nonsynonymous variants increased the risk of obesity in humans." (PMID 28988979, 2017). "However, whether IRX3 gene per se predisposes to obesity in humans and how IRX3 regulates the browning process remains unclear." (PMID 28988979, 2017).